CD80 (CD80 molecule)
Diseases named in the same sentence as CD80 in open-access papers (continued):
Sharing a sentence is not in itself a finding about the gene and the disease.
metastatic melanoma (8 papers, 2014 to 2024). A melanoma that has spread from its primary site to another anatomic site. "Our previous study in metastatic melanoma and the present findings in HNSCC have showed that elevated levels of circulating PD-L1+ sEVs, the interaction protein for both PD-1 and CD80, are also associated with the anti-PD-1 response and survival rate." (PMID 38719909, 2024). "The first checkpoint inhibitor against cytotoxic T lymphocyte protein 4 (CTLA-4, CD152, ipilimumab; Bristol-Myers Squibb; interacts with CD80 (B7.1), alternatively with CD86 (B7.2)) has been approved in March 2011 in the US for the treatment of patients with unresectable or metastatic melanoma." (PMID 37174080, 2023).
vitiligo (8 papers, 2016 to 2025). Generalized well circumscribed patches of leukoderma that are generally distributed over symmetric body locations and is due to autoimmune destruction of melanocytes. "GWAS meta analysis (GWAS-MA) of vitiligo has showed suggestive association of SNP rs4330287 and imputed SNP rs59374417 in CD80, which was confirmed by replication study and overall meta-analysis." (PMID 26870082, 2016). "In vitiligo, DAMPs enhance the maturation of DCs, elevating the expression levels of co-stimulatory molecules such as CD80 and CD86, thereby augmenting their antigen-presenting capabilities." (PMID 41169396, 2025). "In vitiligo, activated DCs migrate to regional lymph nodes, where they upregulate co-stimulatory molecules like CD80 and CD86, present melanocyte antigens to T cells, and provide the second signal for full activation." (PMID 41169396, 2025). "A previous study has shown that the proportion of CD80+ monocytes is significantly elevated in the peripheral blood of individuals with vitiligo compared to healthy controls." (PMID 38887286, 2024). "A previous study reported a significant increase in the proportion of CD80+ monocytes in peripheral blood of vitiligo patients compared with HCs, suggesting that monocytes are involved in vitiligo development, but their function has not been investigated." (PMID 38077333, 2023). "A previous study reported that the proportion of CD80+ monocytes was significantly higher in the peripheral blood of vitiligo patients than in that of healthy controls, suggesting that monocytes may play a role in the development of vitiligo." (PMID 41438750, 2025). "Interestingly, flow cytometric analysis has found a significantly increased percentage of CD80+ monocytes in the vitiligo group compared with the controls, which may indicate alteration of monocytes function in vitiligo." (PMID 35884944, 2022). "Flow cytometric analysis has found that the percentage of CD80+ monocytes are significantly increased in the vitiligo group compared with the controls, which may indicate alterations of monocyte function in the pathogenesis of vitiligo." (PMID 26870082, 2016). "The expression of co-stimulatory molecules on DCs, including CD80 and CD86, is notably increased in vitiligo patients, enhancing their antigen-presenting ability and promoting the activation and proliferation of T cells, particularly CD8+ T cells, which contribute to the destruction of melanocytes." (PMID 41169396, 2025). "Simultaneously, melanocytes express co-stimulatory molecules (e.g., CD40, CD80) and adhesion molecules (e.g., ICAM-1), enabling them to present self-antigens to T cells, thereby promoting T cell proliferation and activation, ultimately contributing to vitiligo progression." (PMID 41169396, 2025).
endometriosis (7 papers, 2020 to 2025). The growth of functional endometrial tissue in anatomic sites outside the uterine body. "In our study, we found that the proportion of CD80+ macrophages decreased after macrophages were treated with exosomes of the uterine aspirate fluid from patients with endometriosis." (PMID 36551866, 2022). "The results revealed that exosomes of the uterine aspirate fluid in patients with endometriosis decreased the proportion of CD80+ macrophages compared with the control and PBS." (PMID 36551866, 2022). "Accordingly, PF from the patients with endometriosis was reported to downregulate the expression of the MHC class II molecules as well as CD80 and CD86 costimulatory molecules in monocytes." (PMID 34360900, 2021). "We found that both the MΦ1 (CD80+/CD163−) and mixed MΦ1/MΦ2 (CD80+/CD163+) subtypes were significantly decreased in women with endometriosis, while the MΦ2 (CD80−/CD163+) subtype was significantly increased." (PMID 32572831, 2020). "Our research found that exosomes of the uterine aspirate fluid from endometriosis could reduce the proportion of CD80+ macrophages." (PMID 36551866, 2022). "Exosomes from endometriosis could decrease the proportion of CD80+ macrophages whereas treatment with anisomycin could increase the CD80+ macrophage level." (PMID 36551866, 2022). "The expression of miR-210-3p was increased in both exosomes and the eutopic endometrium in patients with endometriosis through miRNA sequencing, which could also reduce the proportion of CD80+ macrophages." (PMID 36551866, 2022). "In addition, we found that exosomes from the uterine cavity in endometriosis could decrease the proportion of CD80+ macrophages by inhibiting the JNK pathway." (PMID 36551866, 2022). "Still, in patients with endometriosis, the percentage of CD192+ cells was higher and significantly correlated with the counts of pro-inflammatory activated CD80+ monocytes in the blood (r = 0.805, p < 0.001) and in the peritoneal fluid (r = 0.844, p < 0.001)." (PMID 39056769, 2024). "Here, rhIL-37 treatment significantly increased the proportion of CD40-, CD80-, CD86-, and MHC II-positive DCs in the blood of the mice with endometriosis, suggesting that rhIL-37 promoted DCs maturation in endometriosis." (PMID 34429116, 2021). "Therefore, we examined the distribution and abundance of the MΦ2a (CD80−/CD163+/CD206+) and MΦ2b (CD80−/CD163+/CD86+) subtypes in controls and endometriosis in the CD14+low/CD68+low and CD14+high/CD68+high subpopulations." (PMID 32572831, 2020). "Interestingly, in addition to MΦ1 and MΦ2 macrophages, we also identified a mixed MΦ1/MΦ2 subtype that was both CD80 and CD163 positive and present in the PF of both women with and without endometriosis (top)." (PMID 32572831, 2020).
glioblastoma (7 papers, 2018 to 2025). The most malignant astrocytic tumor (WHO grade IV). "In the glioblastoma TME, higher expression of CD80 and CD86 was associated with shorter progression-free survival (PFS)." (PMID 40724825, 2025). "Elevated CD86 mRNA expression has recently been demonstrated as a potential prognostic biomarker for glioblastoma, and significantly enhanced CD80 and CD86 mRNA expression was detected in peripheral blood samples of CRC patients." (PMID 39456247, 2024). "We found that the CD80:CD206 ratio decreased significantly when co-culturing FNDC4-overexpressing glioblastoma cells with M1 macrophages." (PMID 36056336, 2022). "Furthermore, we examined the expression of surface molecules MHCII, CD80, and CD86 in infiltrating CD45+CD103+ DCs in the Control and sh-Rab27a3 groups of glioblastoma." (PMID 39192971, 2024). "For example, tumour-associated macrophages from glioblastoma have been reported to lack the costimulatory molecules CD86, CD80 and CD40, suggesting that they are not able to effectively support activation of T cells." (PMID 34676050, 2021).
malaria (7 papers, 2006 to 2019). Malaria is a serious and sometimes fatal disease caused by a parasite that commonly infects a certain type of mosquito which feeds on humans. "In pregnancy-associated malaria, iRBCs preferentially accumulate in the placenta leading to higher parasite exposure of placental compared to peripheral blood monocytes, and CD80 and CD86 expression was higher in placental compared to peripheral monocytes." (PMID 19680449, 2009). "Malaria-exposed women had increased frequencies of CD80+ active and raMBCs and CD86+ resting atypical and classical MBC compared to non-exposed." (PMID 28878766, 2017). "Altered DCs and monocytes, and reduced frequency and low expression of the CD86 and CD80 activation markers, are observed in malaria-infected pregnant women, suggesting DC migration to lymphoid organs." (PMID 28049536, 2017). "It has been found that blocking the CD80/CD86 signaling pathway disrupts the Th1/Th2 balance in the Plasmodium chabaudi AS malaria model." (PMID 22348301, 2012). "Hemozoin, the malaria pigment, may induce DC activation and maturation via the expression of CD80, CD86 and chemokine receptors CXCR4, promoting their migration to lymphoid organs." (PMID 28049536, 2017). "We also observed that malaria-exposed individuals had higher frequencies of CD80+ raMBC and CD80+ aaMBC than the non-exposed individuals but only raMBC had higher proportions of CD86+ cells in the exposed group." (PMID 28878766, 2017). "Individuals highly exposed to malaria had more PD1+, CD95+, CD80+, CD71+, and CD40+ aaMBC than malaria non-exposed individuals." (PMID 28878766, 2017). "DCs incubated with RBCs or pRBCs did not, however, increase expression of MHC class II, CD40, CD80 and CD86, indicating that malaria parasites do not induce DC activation directly." (PMID 16611373, 2006).
neuroblastoma (7 papers, 2003 to 2023). Neuroblastoma (NB) is the most common solid, extracranial childhood tumor. "The successful treatment of cancer with inhibition of the CTLA-4, PD-1, PD-L1, and CD80/86 pathways in adults was the basis for our exploration into additional checkpoint molecule expression in neuroblastoma." (PMID 35159017, 2022). "Owing to oxidative stress, neuroblastoma cell lines, which lack CD80, showed increased sensitivity to cytotoxic agents when transduced with GFP, eGFP, and YFP." (PMID 27435468, 2016). "Ewing sarcoma cDCs showed significantly lower percentages of CD83-, CD86-, and TNFSF9-expressing cells and Ewing sarcoma Mφ had significantly lower CD70-, CD80-, CD83-, and TNFSF9-expressing cells, than neuroblastoma." (PMID 37823774, 2023). "We have developed a cell-based vaccine that features the expression of both CD80 and CD86 on the surface of a murine neuroblastoma cell line." (PMID 17397536, 2007). "It was demonstrated that, independent from immunogenicity, both CD80-negative and CD80-transduced neuroblastoma cells had significantly enhanced sensitivity to cytotoxic anticancer agents when transduced with GFP, eGFP, and YFP." (PMID 27435468, 2016). "CD80 and CD86 are critical to the function of T cells and are not typically present on the surface of neuroblastoma cells." (PMID 35326601, 2022). "Here, we have investigated the expression of costimulatory molecules (CD40, CD80, CD86, PD-1L, B7H2, OX40L and 4-1BBL) in human neuroblastoma (NB) cells, since virtually no information is available on this issue." (PMID 12771917, 2003).
renal cell carcinoma (7 papers, 2014 to 2024). "For instance, in a clinical phase I study launched by Westermann and colleagues, they immunized renal cell cancer (RCC) patients with IL-7 and CD80 genes cotransfected RCC tumor cells cancer vaccine." (PMID 36389666, 2022). "A phase I study demonstrated safety of a vaccine against renal cell carcinoma (RCC) containing tumor cells expressing RCC26/IL-7/CD80; while they did not observe increased Th1 specific immune responses, they did find higher levels of Th2 mediated IL-10 expression in patients who responded." (PMID 25268164, 2014).
colorectal tumor (6 papers, 1998 to 2025). "Moreover, given the described reduced risk of relapse in colorectal tumors with higher immunoscore, it would be important to explore possible associations between the infiltration of CD80+ cells and cytotoxic or memory T cells." (PMID 31481956, 2019). "Treatment with IR780+L in colorectal tumor‐bearing mice elevated the proportion of mature DCs, characterized by CD80+ and CD86+ expression in CD11c+ DCs." (PMID 39525955, 2024). "Overall, these results support a protective role of CD80+ cells at the IF of colorectal tumors for relapse." (PMID 31481956, 2019). "We have previously shown that the SNs of colorectal tumor cells that had been treated with RT plus HT also induce a significant up-regulation of expression of CD80 and CCR7 on DCs and that Hsp70 is one mediator of it." (PMID 26383236, 2015). "Importantly, despite the low infiltration of CD80+ cells in colorectal tumors, multivariate logistic regression revealed a protective role of these cells regarding the risk for relapse." (PMID 31481956, 2019). "The absence of autologous tumour-specific cytolytic T-cell (CTL) activity may be due to the poor immunogenicity of colorectal tumour cells, which we found expressed only low levels of MHC I antigens and CD54 and failed to express MHC II antigens or the co-stimulatory molecules CD80, CD86 or CD106." (PMID 9569042, 1998). "The lack of CD70, CD80, or CD86 expression on ILCs in colorectal tumors could, therefore, be the consequence of signals counteracting the effect of inflammasome-associated cytokines in the local microenvironment." (PMID 32341343, 2020).
diabetic nephropathy (6 papers, 2015 to 2023). "Few studies have illuminated the genetic role of T cell costimulatory molecule CD28/CD80/CTLA4 variants in diabetic kidney disease (DKD) susceptibility." (PMID 33958973, 2021). "Recent studies have found that CD80 is expressed in renal tissue in several types of glomerulonephritis, such as lupus nephritis, immunoglobulin A nephropathy, diabetic nephropathy, and Fabry disease, in addition to MCD." (PMID 30083478, 2018).
lupus nephritis (6 papers, 2010 to 2023). Glomerulonephritis in the context of systemic lupus erythematosus. "In that study, urinary CD80 was elevated even in patients with lupus nephritis who had high levels of proteinuria." (PMID 36673014, 2023). "Patients with lupus nephritis showed significantly higher levels of CD80 expression on CD4+CCR6+ cells in comparison to healthy controls (22.13 ± 10.58% vs. 18.86 ± 3.82%, P = 0.02)." (PMID 20653937, 2010). "Patients with and without active disease, as assessed by SLEDAI, and patients with and without lupus nephritis, proven by renal biopsy, were analysed for CD80 expression on CD4+CCR6+ cells." (PMID 20653937, 2010).
lymph node metastasis (6 papers, 2018 to 2024). "Indeed, these observations were also in contrast with the previously reported results on esophageal cancer, where the lower CD80 protein level was associated with the presence of lymph node metastasis." (PMID 30123257, 2018). "Furthermore, a relationship between clinical stage and Breslow thickness (<2mm/≥2mm), tumor ulceration, lymph node metastasis, and CD80 and CD86 expression was also identified." (PMID 37614091, 2024). "Lastly, lymph node metastases were found to associate with increased PD-L2, while the reduced CD80 mRNA levels were related to the absence of lymph node metastases." (PMID 30123257, 2018). "CD80 expression was higher in patients who did not have lymph node metastasis." (PMID 37614091, 2024).
myeloid leukemia (6 papers, 2014 to 2021). A clonal proliferation of myeloid cells and their precursors in the bone marrow, peripheral blood, and spleen. "In a murine model of myeloid leukemia, CD80-CTLA-4 interaction resulted in evasion of CD8+ T cell-mediated immune response." (PMID 33801964, 2021). "While data are lacking on the expression of CD80 and CD86 in HTLV-1 infection and pathogenesis, IFN-α enhanced CD80 expression in vitro in myeloid leukemia, while IFN-β has been shown to regulate CD80 and CD86 in vivo and in vitro in MS." (PMID 24472094, 2014). "As previously demonstrated by our group, myeloid leukemia cells can provide direct costimulation via CD80, CD86, and ICOS-LG molecules, and these malignant blasts are proficient in utilizing elaborate immune evasion strategies including the adaptive resistance and T-cell exhaustion." (PMID 31406210, 2019). "An in vivo study of murine myelogenous leukemia suggested that blockade of B7-1 (CD80) and not B7-2 (CD86) by CTLA-4 contributed to the attenuation of anti-leukemic immunity." (PMID 33669431, 2021).
colon adenocarcinoma (5 papers, 2015 to 2022). "Finally, in the AOM/DSS-induced colonic adenocarcinoma model CD80 signaling inhibition significantly increased the frequency and extension of high-grade dysplasia, whereas enhancing CD80 activity with an anti-CTLA4 antibody significantly decreased colonic dysplasia." (PMID 25595911, 2015). "To show the ability of IEC to directly modulate lymphocyte activation through CD80 signaling, we co-cultured IEC from healthy colonic mucosa with syngeneic lymphocytes extracted from pericolonic lymph nodes of patients undergoing surgery for non neoplastic disease and for colonic adenocarcinoma." (PMID 25595911, 2015).
dysplasia (5 papers, 2015 to 2021). A usually neoplastic transformation of the cell, associated with altered architectural tissue patterns. "In the AOM model, CD80 impairment by administration of neutralizing antibodies or use of CD80 knockout mice enhanced dysplasia development." (PMID 31072360, 2019). "Our experimental model allowed us to demonstrate that interfering with early CD80 signaling - by neutralizing antibodies administration or use of a knockout strain - results in a significant augmentation of dysplasia extension in the colonic mucosa of AOM-treated mice." (PMID 31072360, 2019). "Furthermore, the rate of CD80+ epithelial cells was significantly higher in UC patients with dysplasia compared with non UC-related dysplasia." (PMID 25595911, 2015). "Notably, lack of functional CD80, determined by genetic background in CD80−/− mice or by specific antibody block, caused a significant increase in dysplasia extension in AOM treated mice." (PMID 31072360, 2019). "However, CD80 signaling augmentation by means of anti-CTLA4 administration failed to completely eradicate the dysplasia." (PMID 25595911, 2015).
fibrosarcoma (5 papers, 2010 to 2025). A malignant mesenchymal fibroblastic neoplasm affecting the soft tissue and bone. "The results also revealed that FDX1 was significantly positively correlated with expression of costimulatory molecules CD80 and CD86 in fibrosarcoma." (PMID 38938647, 2024). "Venetoclax also induced other maturation markers including CD80 and CD83 on cDC1 (and cDC2 in some cases) cells from the blood, tumor and both the tumor-draining and non-draining lymph nodes of mice bearing orthotopic MCA205 fibrosarcomas." (PMID 37623817, 2023).
glomerulonephritis (5 papers, 2015 to 2021). A renal disorder characterized by damage in the glomeruli. "Similar results were obtained for glomerulonephritis, IgG deposits in kidneys, and the activation status of innate and adaptive immune cells (expression of CD80 and CD69 on cDC2s and CD4+ T cells, respectively)." (PMID 34282144, 2021).
Granuloma (5 papers, 2010 to 2022). A compact, organized collection of mature mononuclear phagocytes, which may be but is not necessarily accompanied by accessory features such as necrosis. "We next evaluated the effect of hypoxia on the expression of CD80 and CD86 co-stimulatory molecules and on HLA-DR as these markers are associated with antigen presentation and expressed by epithelioid cells in sarcoidosis granuloma." (PMID 34456926, 2021). "By flow cytometric analysis, we found that CD11c+ cells in chronic granulomas had lower expression of MHCII and co-stimulatory molecules CD40, CD80 and CD86, and higher expression of inhibitory molecules PD-L1 and PD-L2 compared to CD11c+ cells from acute granulomas." (PMID 20625513, 2010).